SPANXB1 (SPANX family member B1)
Synonyms: CT11.2; SPANX-B; SPANXB; SPANXB2; SPANXF1; B1; SPANXF2
Tractability: PROTAC: ubiquitination databases record sites on it.
Gene: Protein-coding gene on chromosome X (141,002,594 to 141,003,706, forward strand). Ensembl gene ENSG00000227234.
Subcellular location: Cytoplasm; Nucleus
Subcellular location (Human Protein Atlas): Nucleoplasm; Vesicles
Gene Ontology:
Molecular function: protein binding
Biological process: spermatid development
Cellular component: nucleus; cytoplasm
Homologues: Paralogues in human: SPANXA1 (80% identical), SPANXA2 (80% identical), SPANXC (76% identical), SPANXD (74% identical).
Diseases named in the same sentence as SPANXB1 in open-access papers:
SPANXB1 is named in the same sentence as 16 diseases in open-access papers, as found by Europe PMC text mining. Sharing a sentence is not in itself a finding about the gene and the disease. The quoted sentences say what the papers report.
breast carcinoma (5 papers, 2019 to 2025). "The present study investigated the role of SPANXB1, which is significantly upregulated in brain-seeking breast cancer cells, in the process of brain metastasis and its underlying molecular mechanism." (PMID 40885703, 2025). "In addition to evidence confirming that the F2 cells showed upregulation of genes and gene pathways associated with cancer or breast cancer metastases, we also report the novel finding that the SPANXB1 gene was upregulated in the F1/F2 subpopulations." (PMID 35614362, 2022). "By targeting the molecular mechanism of SPANXB1, this study offers a new therapeutic strategy for breast cancer patients with brain metastasis." (PMID 40885703, 2025). "Among these, the function and mechanism of SPANXB1 in breast cancer brain metastasis (BCBM) remain poorly understood." (PMID 40885703, 2025). "Functional assays revealed that SPANXB1 promoted breast cancer cell invasion, migration, vasculogenic mimicry (VM) formation, and blood-brain barrier (BBB) extravasation, thereby accelerating the process of brain metastasis." (PMID 40885703, 2025). "SPANXB1 is highly expressed in various malignant tumors, including breast cancer, lung cancer, melanoma, prostate cancer, bladder cancer, renal cell carcinoma, and testicular germ cell tumors." (PMID 40885703, 2025). "We further used animal models to elucidate the impact of SPANXB1 on the ability of breast cancer cells to traverse the BBB." (PMID 40885703, 2025). "In conclusion, metformin significantly inhibits the brain metastasis potential of BR cells by suppressing the expression of SPANXB1, suggesting that SPANXB1 is a key molecular target for metformin on breast cancer cells." (PMID 40885703, 2025). "We explored the effects of SPANXB1 on promoting breast cancer cell migration, invasion, VM, and BBB extravasation and further demonstrated that these effects were achieved through the upregulation of MMP1 expression." (PMID 40885703, 2025). "SPANXB1 has been shown to increase the migration and invasion of breast cancer cells and promote tumor metastasis." (PMID 40885703, 2025). "Our study demonstrates that metformin exerts dose-dependent inhibitory effects on both mRNA and protein expression of SPANXB1 in breast cancer cells." (PMID 40885703, 2025). "To investigate how SPANXB1 affects breast cancer cell brain metastasis, we performed RNA-seq to compare gene expression of SPANXB1-knockdown BR cells with control BR cells." (PMID 40885703, 2025). "Overall, these findings suggest that SPANXB1 promotes the extravasation of breast cancer cells across the BBB by regulating the disruption of tight junctions in brain endothelial cells induced by tumor cells." (PMID 40885703, 2025). "In the present study, we examined SPANXB1 expression in multiple breast cancer cell lines and found that SPANXB1 expression was low in MCF-7, 453, 436, and 231 cells but significantly increased in BR cells." (PMID 40885703, 2025). "Our results demonstrated that SPANXB1 was highly expressed in brain-tropic breast cancer cells and brain metastasis samples." (PMID 40885703, 2025). "In light of its pro-migratory effect on 231-BR cells as well as its prognostic value in metastasis-free survival of breast cancer patients, SPANXB1 was therefore also considered as a key gene in the present study." (PMID 35096583, 2021). "To assess SPANXB1 mRNA expression pattern in overall BCa and TNBCs, we analyzed SPANXB1 expression data (transcriptome) in BCa patients from the TCGA’s Breast Cancer project (TCGA-BRCA)." (PMID 31406142, 2019). "SPANXB1 overexpressing breast cancer cells with an enhanced SPANXB1:SH3GL2 ratio achieved pulmonary metastasis within 5 weeks, whereas controls cells failed to do so." (PMID 31406142, 2019). "Consequently, SPANXB1 facilitated the extravasation of breast cancer cells across the BBB and promoted the progression of brain metastasis." (PMID 40885703, 2025).
breast carcinoma (continued). "To investigate whether SPANXB1 influences the process of breast cancer cells crossing the BBB, we conducted adhesion and trans-endothelial migration assays." (PMID 40885703, 2025). "In summary, these findings suggest that SPANXB1 may promote brain metastasis by facilitating breast cancer cell migration, invasion, and VM formation." (PMID 40885703, 2025). "To further investigate whether the role of SPANXB1 in promoting breast cancer cell extravasation is mediated through MMP1, we conducted rescue experiments." (PMID 40885703, 2025). "For instance, SPANXB1 had previously been implicated as an immunogenic tumor antigen in breast cancer while SAA 2 and C15orf4 8 were associated with poorer prognosis in breast cancers." (PMID 35614362, 2022). "It should be noted that although the expression level of SPANXB1 was very low in breast cancer patients as well as in most of the human cancer cell lines, it showed a very high expression in the brain metastatic 231-BR cells as compared with its parental MDA-MD-231." (PMID 35096583, 2021). "In summary, this study demonstrated that SPANXB1 promotes MMP1 expression and subsequently induces migration, invasion, VM formation and BBB extravasation in breast cancer cells, thus promoting BCBM progression." (PMID 40885703, 2025). "In breast cancer (GSE77308), KRT19 and SPANXB1 were shown to be correlated with several functional states." (PMID 35096583, 2021). "Furthermore, we observed that SPANXB1 upregulates the expression of MMP1, which subsequently enhances the transmigration of breast cancer cells across the BBB and accelerates the progression of BCBM." (PMID 40885703, 2025). "Because the overexpression of SPANXB1 promotes cell migration/invasion of non-metastatic breast cancer cells, EV-mediated transfer of SPANXB1 may contribute to TNBC metastasis." (PMID 36835116, 2023). "To explore the expression of SPANXB1 in human BCBM, we first conducted HE staining on human adjacent non-cancerous tissues, primary breast cancer tissues and brain metastatic tumor samples." (PMID 40885703, 2025).
melanoma (3 papers, 2021 to 2025). A malignant, usually aggressive tumor composed of atypical, neoplastic melanocytes. "SPANXB1 has been reported to be expressed in melanoma and carcinomas of breast, lung, ovary, colon, and bladder." (PMID 35096583, 2021). "SPANXB1 tumor-specific expression pattern and demonstrated ability to induce CD8+ T cell cytotoxic responses in melanoma and multiple myeloma provide theoretical foundation for its immunotherapeutic applications." (PMID 40885703, 2025).
benign breast disease (1 paper, 2019). "However, we did not detect SPANXB1 expression in the circulating sEVs isolated from healthy women (N = 9) or women with benign breast disease (N = 7)." (PMID 31406142, 2019).
breast tumors (1 paper, 2025). "For clinical validation, while we confirmed elevated expression of SPANXB1 and its downstream effectors (YY1, H3R17me2, MMP1) in both primary breast tumors and brain metastases, the small sample size (n = 5 per group) necessitates validation in larger clinical cohorts." (PMID 40885703, 2025).
colorectal cancer (1 paper, 2023). A primary or metastatic malignant neoplasm that affects the colon or rectum. "Our RNA-Seq analysis also found that 5’-Aza-CdR exposure resulted in overexpression of multiple CT antigens in gastric cancer and colorectal cancer, including SSX1, TKTL1, SPANXB1, PNMA5, PNMA6E, GAGE12J, and PRSS56." (PMID 37400936, 2023).
triple-negative breast carcinoma (1 paper, 2022). An invasive breast carcinoma which is negative for expression of estrogen receptor (ER), progesterone receptor (PR), and human epidermal growth factor receptor 2 (HER2). "In triple negative breast cancers, SPANXB1 expression has been identified in circulating small extracellular vesicles and is thought to be acted upon by metastasis suppressor SH3GL2." (PMID 35614362, 2022).
cancer (4 papers, 2019 to 2025). A tumor composed of atypical neoplastic, often pleomorphic cells that invade other tissues. "Further comprehensive mechanistic studies are needed to determine the exact extent with which SPANXB1 is associated with cancer metastasis." (PMID 35614362, 2022). "KRT19, FKBP10, GSK3B, and SPANXB1 have been investigated at the single-cell level in 9, 10, 16 and 3 types of cancer, respectively." (PMID 35096583, 2021). "Expression pattern of SPANXB1 was determined using matched primary cancer, lymph node metastatic tissues and circulating small extracellular vesicles (sEVs)." (PMID 31406142, 2019). "The SPANXB1 gene is known to play a role in spermatogenesis but has not previously been associated with cancer metastasis." (PMID 35614362, 2022). "At the same time, monitoring the expression pattern of SPANXB1 in cancer tissues and sEVs may serve as a useful biomarker for disease monitoring and surveillance." (PMID 31406142, 2019). "Here, we examined whether SPANXB1 affected the VM formation ability of cancer cells." (PMID 40885703, 2025). "KRT19 (AUC = 0.855, CI = 0.825 - 0.885) and FKBP10 (AUC = 0.836, CI = 0.808 - 0.864) had a certain accuracy in predicting cancer and normal, and the predictive abilities of GSK3B (AUC = 0.654, CI = 0.613 - 0.696) and SPANXB1 (AUC = 0.682, CI = 0.650 - 0.714) were less accurate." (PMID 35096583, 2021).
tumor (4 papers, 2019 to 2025). "Thus, SPANXB1 loss with rescued SH3GL2 expression in SPANXB1-KD cells not only prevents primary tumor growth but also their progression to metastasis." (PMID 31406142, 2019). "The SPANXB1 overexpressing MCF-7 cells achieved higher primary tumor growth in 5 weeks compared to the controls." (PMID 31406142, 2019). "An increased expression ratio of SH3GL2:SPANXB1 was evident in the primary tumor tissues obtained from the SPANXB1-KD mice." (PMID 31406142, 2019). "To assess the expression pattern of SPANXB1 in primary and metastatic TNBCs, we performed IHC analysis of paired normal/tumor and matched positive lymph node tissues (FFPE), from 15 TNBC subjects." (PMID 31406142, 2019). "The SPANXB1-KD cells exhibited reduced (p = 0.0005–0.006) primary tumor growth at the mammary fat pad compared to the control groups." (PMID 31406142, 2019). "To examine their behavior in vivo, we assessed primary tumor growth and spontaneous metastasis pattern of SPANXB1-KD MDA-MBA-231 cells by implanting them orthotopically in the mammary fat pad of female NSG mice." (PMID 31406142, 2019). "First, we explored the effects of SPANXB1 on tumor cell-related biological functions in vitro." (PMID 40885703, 2025). "Notably, SPANXB1 is a cancer-testis antigen (CTA), a class of tumor-associated antigens that is specifically expressed in a variety of human tumors and normal testes." (PMID 40885703, 2025). "Three of the identified key genes (FKBP10, KRT19, and SPANXB1) negatively correlated with the infiltration of CD8+ T cells, which is the lymphocytes primarily responsible for immune-mediated tumor cell death." (PMID 35096583, 2021). "The SPANXB1-overexpressing primary tumor tissues exhibited a highSPANXB1:SH3GL2expression ratio as opposed to the SPANXB1 depleted TNBC cells." (PMID 31406142, 2019). "A number of metastatic tumor foci were noted in the lung of the mice implanted with SPANXB1 overexpressing MCF-7 cells but no microscopic lesions were evident in the mice implanted with control MCF-7 cells." (PMID 31406142, 2019). "For the first time, we demonstrated that SPANXB1 can upregulate MMP1 by modulating YY1 and histone H3R17me2 modifications, thus providing a novel insight into the role of SPANXB1 as a chromatin-binding protein and its potential as a therapeutic target for managing tumor metastasis." (PMID 40885703, 2025).
SPANXB1 also shares sentences with these, for which no sentence is quoted: asthenospermia (1 paper); colon cancer (1); gastric cancer (1); Infertility (1); metastasis (1); multiple myeloma (1); ovarian carcinoma (1); prostate carcinoma (1).